DCAF1 (DDB1 and CUL4 associated factor 1)
Description:
Acts both as a substrate recognition component of E3 ubiquitin-protein ligase complexes and as an atypical serine/threonine-protein kinase, playing key roles in various processes such as cell cycle, telomerase regulation and histone modification. Probable substrate-specific adapter of a DCX (DDB1-CUL4-X-box) E3 ubiquitin-protein ligase complex, named CUL4A-RBX1-DDB1-DCAF1/VPRBP complex, which mediates ubiquitination and proteasome-dependent degradation of proteins such as NF2. Involved in the turnover of methylated proteins: recognizes and binds methylated proteins via its chromo domain, leading to ubiquitination of target proteins by the RBX1-DDB1-DCAF1/VPRBP complex. The CUL4A-RBX1-DDB1-DCAF1/VPRBP complex is also involved in B-cell development: DCAF1 is recruited by RAG1 to ubiquitinate proteins, leading to limit error-prone repair during V(D)J recombination (By similarity). Also part of the EDVP complex, an E3 ligase complex that mediates ubiquitination of proteins such as TERT, leading to TERT degradation and telomerase inhibition. The EDVP complex also mediates ubiquitination and degradation of CCP110. Also acts as an atypical serine/threonine-protein kinase that specifically mediates phosphorylation of 'Thr-120' of histone H2A (H2AT120ph) in a nucleosomal context, thereby repressing transcription. H2AT120ph is present in the regulatory region of many tumor suppresor genes, down-regulates their transcription and is present at high level in a number of tumors. Involved in JNK-mediated apoptosis during cell competition process via its interaction with LLGL1 and LLGL2. By acting on TET dioxygenses, essential for oocyte maintenance at the primordial follicle stage, hence essential for female fertility (By similarity). (Microbial infection) In case of infection by HIV-1 virus, it is recruited by HIV-1 Vpr in order to hijack the CUL4A-RBX1-DDB1-DCAF1/VPRBP function leading to arrest the cell cycle in G2 phase, and also to protect the viral protein from proteasomal degradation by another E3 ubiquitin ligase. The HIV-1 Vpr protein hijacks the CUL4A-RBX1-DDB1-DCAF1/VPRBP complex to promote ubiquitination and degradation of proteins such as TERT and ZIP/ZGPAT. (Microbial infection) In case of infection by HIV-2 virus, it is recruited by HIV-2 Vpx in order to hijack the CUL4A-RBX1-DDB1-DCAF1/VPRBP function leading to enhanced efficiency of macrophage infection and promotion of the replication of cognate primate lentiviruses in cells of monocyte/macrophage lineage.
Synonyms: VprBP; KIAA0800; RIP; MGC102804
Tractability: Small molecule: a structure with a bound ligand is known. PROTAC: ubiquitination databases record sites on it.
Target class: Enzyme; Transferase
Chemical probes: OICR-41103 (high quality), OICR-8268 (high quality)
Gene: Protein-coding gene on chromosome 3 (51,395,867 to 51,500,088, reverse strand). Ensembl gene ENSG00000145041.
Subcellular location: Cytoplasm; Nucleus; Cytoplasm, cytoskeleton, microtubule organizing center, centrosome
Subcellular location (Human Protein Atlas): Nucleoplasm; Nucleoli fibrillar center
Pathways (Reactome):
Immune System: Antigen processing: Ubiquitination & Proteasome degradation
Gene Ontology:
Molecular function: histone H2AT120 kinase activity; nuclear estrogen receptor binding; protein binding; ubiquitin-like ligase-substrate adaptor activity; protein serine kinase activity; protein serine/threonine kinase activity
Biological process: cell competition in a multicellular organism; negative regulation of transcription by RNA polymerase II; positive regulation of protein catabolic process; post-translational protein modification; proteasome-mediated ubiquitin-dependent protein catabolic process; B cell differentiation; V(D)J recombination; chromatin remodeling; protein ubiquitination
Cellular component: centrosome; COP9 signalosome; Cul4-RING E3 ubiquitin ligase complex; Cul4A-RING E3 ubiquitin ligase complex; cytoplasm; fibrillar center; nucleoplasm; nucleus; Cul4B-RING E3 ubiquitin ligase complex
Genetic constraint (gnomAD): Loss-of-function variants: 13 observed, 114.87 expected, observed/expected ratio (o/e) 0.11, 90% interval 0.073 to 0.18. The upper end of that interval is the gene's LOEUF score, 0.18, which puts it in group 1 of 6, group 1 being the genes least tolerant of losing a copy. Missense variants: 867 observed, 1,556.6 expected, observed/expected ratio (o/e) 0.56, 90% interval 0.53 to 0.59. Synonymous variants: 529 observed, 573.4 expected, observed/expected ratio (o/e) 0.92, 90% interval 0.86 to 0.99.
Homologues: Orthologues: chimpanzee DCAF1 (100% identical), macaque DCAF1 (99% identical), rabbit DCAF1 (99% identical), mouse Dcaf1 (98% identical), dog DCAF1 (98% identical), pig DCAF1 (98% identical), rat Dcaf1 (97% identical), guinea pig DCAF1 (95% identical), Drosophila melanogaster mahj (37% identical), Caenorhabditis elegans dcaf-1 (35% identical).
Diseases named in the same sentence as DCAF1 in open-access papers:
DCAF1 is named in the same sentence as 37 diseases in open-access papers, as found by Europe PMC text mining. Sharing a sentence is not in itself a finding about the gene and the disease. The quoted sentences say what the papers report.
HIV-1 infection (13 papers, 2009 to 2025). The type species of lentivirus and the etiologic agent of acquired immunodeficiency syndrome (AIDS). "The HIV Vpx/CUL4/DCAF1/RBX1 complex relieves inhibition of HIV-1 infection of macrophages by mediating SAMHD1 protein degradation." (PMID 38005838, 2023). "The presence of Vpr enhances HIV-1 infection by promoting LAPTM5 degradation via the DCAF1/proteasome, thus releasing Env from the Golgi complex traffic to the plasma membrane for HIV-1 progeny assembly." (PMID 34140527, 2021). "We further investigated whether Vpr exploits DCAF1 to induce ciTRAN during HIV-1 infection." (PMID 40632811, 2025). "However, the role of DCAF1 in HIV-1 infection remains to be examined." (PMID 22570689, 2012). "In the context of HIV-1 infection, however, Vpr has been shown to directly bind DCAF1, earning it the name “Vpr-binding protein” (VprBP)." (PMID 38543785, 2024). "It has been reported that DCAF1/VprBP is recruited by HIV-2/SIVsmm/mac Vpx to hijack the CUL4–DDB1 E3 ubiquitin ligase complex for degradation of host-restrictive factor SAMHD1, facilitating HIV-1 infection in myeloid cells." (PMID 24932481, 2014). "Our result is consistent with a recent report by Pertel and colleagues, wherein they demonstrated that Vpr+ single-cycle HIV-1 infection of MDDCs was independent of DCAF1." (PMID 22570689, 2012). "Furthermore, our data indicated that DCAF1 is not required for Vpr-enhanced HIV-1 infection in HuT/CCR5 cells, which is consistent with a recent report demonstrating that single-cycle HIV-1 infection of MDDCs is independent of DCAF1." (PMID 22570689, 2012).
breast cancer (6 papers, 2017 to 2023). A primary or metastatic malignant neoplasm involving the breast. "We thus speculate that the role of DCAF1-mediated EZH2T367p in colon cancer is distinct from that of p38-mediated EZH2T367p in breast cancer." (PMID 37069142, 2023).
colon cancer (6 papers, 2021 to 2025). "The data presented here now demonstrate the role of DCAF1 in mediating EZH2T367p during the development of colon cancer." (PMID 37069142, 2023). "Given that DCAF1 and EZH2 levels are significantly correlated among colon tumor samples, we also expected the involvement of DCAF1 in catalyzing EZH2T367p during colonic tumorigenesis." (PMID 37069142, 2023). "In an extension of this initial discovery, we also demonstrated that treating colon cancer cells with subtoxic concentrations of EZH2 inhibitor Taz recapitulates the effects of DCAF1 inhibitor albeit somewhat less efficiently." (PMID 37069142, 2023). "We recently reported that DCAF1 is overexpressed and represses gene transcription through H2AT120p in colon cancer cells." (PMID 37069142, 2023). "In agreement with our published data, depletion of endogenous DCAF1 in SW620 colon cancer cells drastically reduced the levels of H2AT120p in chromatin fractions." (PMID 37069142, 2023). "Additional analysis after expressing FLAG-DCAF1 in DCAF1-depleted colon cancer cells clearly showed almost complete restoration of cell growth rates." (PMID 37069142, 2023). "Although our data clearly implicate DCAF1-mediated EZH2T367p in EZH2 stabilization in colon cancer cells, they left open the molecular basis for the observed T367p effects." (PMID 37069142, 2023). "In further support of these data, DCAF1 expression is significantly upregulated in colon cancer patient samples, and this phenomenon correlates well with EZH2T367p levels." (PMID 37069142, 2023). "Given that ER stress response constitutes a key signaling event in cancer development and progression, these findings functionally implicate DCAF1-mediated EZH2T367p in colon cancer." (PMID 37069142, 2023). "In our study, we also found that treatment of colon cancer cells with the selective DCAF1 inhibitor B32B3 reactivates growth regulatory genes and inhibits uncontrolled cell growth." (PMID 37069142, 2023). "Our recent work has shown that DCAF1 (also known as VprBP) is overexpressed in colon cancer and phosphorylates histone H2AT120 to drive epigenetic gene inactivation and oncogenic transformation." (PMID 37069142, 2023). "Since Taz treatment alone did not appreciably alter EZH2 and EZH2T367p levels, these results support the dominant effect of B32B3 over Taz and point to DCAF1-mediated EZH2T367p as a key determinant for H3K27me3-induced oncogenic gene silencing in colon cancer." (PMID 37069142, 2023). "We therefore next asked whether colon cancer cells are more responsive to the combination of DCAF1 inhibitor B32B3 and EZH2 inhibitor Tazemetostat (Taz)." (PMID 37069142, 2023). "However, of particular interest in this regard is the observation that EZH2T367D phospho-mimicking mutant is capable of fully restoring the original growth rates of DCAF1-depleted colon cancer cells." (PMID 37069142, 2023). "DCAF1 is highly expressed in colon cancer cells and catalyzes EZH2T367p." (PMID 37069142, 2023). "Moreover, much higher levels of DCAF1 protein in human colon tumor samples and a strong correlation between protein levels for DCAF1 and EZH2 are further indicative of a DCAF1 role in enhancing EZH2 protein stability in colon cancer cells." (PMID 37069142, 2023). "This led us to speculate that DCAF1-mediated H2AT120p may indirectly influence H3K27me3 in colon cancer cells, because H2AT120 lies close to the H3 N-terminal tail." (PMID 37069142, 2023). "Thus, our study not only identifies EZH2T367p as a biomarker for the prediction of colon cancer but also provides the evidence that targeting DCAF1 kinase activity toward EZH2 is a promising strategy for tackling colon cancer development." (PMID 37069142, 2023). "However, the inability of CHX to decrease EZH2 protein levels in EZH2T367D-transfected, EZH2-depleted SW620 cells supported the view that DCAF1-mediated T367p is sufficient to generate the higher stability of EZH2 in colon cancer cells." (PMID 37069142, 2023).
colon cancer (continued). "The observed effect of B32B3 is suggestive of EZH2-targeted action of DCAF1 in colon cancer cells." (PMID 37069142, 2023). "In extending these studies, we first examined whether other histone modifications are also subject to regulation by DCAF1 in colon cancer cells." (PMID 37069142, 2023). "Furthermore, if EZH2T367D phospho-mimicking mutant is expressed in EZH2-depleted cells, target genes were expressed at significantly lower levels, even lower than in control cells—underscoring the importance of DCAF1-EZH2T367p for target gene inactivation in colon cancer cells." (PMID 37069142, 2023). "A very recent study demonstrated DCAF1-mediated phosphorylation of EZH2 at T367 to augment its nuclear stabilization and enzymatic activity in colon cancer cells." (PMID 40289112, 2025). "We now demonstrate that DCAF1 phosphorylates EZH2 at T367 to augment its nuclear stabilization and enzymatic activity in colon cancer cells." (PMID 37069142, 2023). "In the present study, we show that DCAF1 is overexpressed and phosphorylates EZH2 in colon cancer cells." (PMID 37069142, 2023). "Given the demonstrated reliance of EZH2 stability on DCAF1-mediated T367p and EZH2 function dependent of H3K27me3 in colon cancer cells, it was reasonable to expect greater inhibitory effects of Taz plus B32B3 combination in our assays." (PMID 37069142, 2023). "Here the authors show that DCAF1/VprBP phosphorylates and stabilises EZH2 to induce oncogenic gene silencing and colon cancer growth." (PMID 37069142, 2023). "Our observation of DCAF1-dependent phosphorylation and stabilization of EZH2 at growth regulatory genes suggests a concerted mechanism for the placing of EZH2T367p and H3K27me3 marks in colon cancer cells." (PMID 37069142, 2023). "Furthermore, we provide evidence that pharmacologically targeting DCAF1 and EZH2 in organoid and xenograft models is sufficient to impair their ability to induce oncogenic gene silencing as well as colonic tumor growth." (PMID 37069142, 2023). "Since we detected equivalent EZH2 mRNA levels in control and DCAF1-depleted SW620 and Caco2 cells, these results indicate a role for DCAF1 in mediating the stabilization and accumulation of EZH2 protein in colon cancer cells." (PMID 37069142, 2023). "This is an important finding as it suggests that DCAF1 and EZH2 inhibitors may be combined to achieve a more favorable therapeutic index for colon cancer patients by establishing distinct epigenetic states at growth regulatory genes." (PMID 37069142, 2023). "The importance of DCAF1 with respect to the observed interaction was further confirmed by the finding that DCAF1 knockdown almost completely abrogates the ability of EZH2 to interact with EED and SUZ12 in colon cancer cells." (PMID 37069142, 2023). "We have extended these observations by investigating whether DCAF1 also phosphorylates non-histone proteins as an additional mechanism linking its kinase activity to colon cancer development." (PMID 37069142, 2023). "Ectopic expression of DCAF1 wild type, but not DCAF1K194R kinase-dead mutant, in DCAF1-depleted cells restored the level of EZH2T367p to ~80% of that observed in mock-depleted control cells, a finding in line with the notion that DCAF1 is essential for EZH2T367p process in colon cancer cells." (PMID 37069142, 2023).
prostate carcinoma (5 papers, 2020 to 2024). A carcinoma that arises from epithelial cells of the prostate gland. "VprBP, also known as DCAF1, is a recently identified kinase and plays an important role in downregulating the transcription of tumor suppressor genes as well as increasing the risk for colon and prostate cancers." (PMID 37293029, 2023).
viral infection (5 papers, 2014 to 2025). "Subsequent studies have indicated that Vpx facilitates viral infection in macrophages by recruiting the CRL4(DCAF1) ubiquitin ligase complex and inducing the degradation of an unidentified antiviral factor." (PMID 38888311, 2024). "The DCAF1 E3 ligase has been reported to be hijacked by Vpx or Vpr to degrade SAMHD1 in immune cells upon viral infection." (PMID 35803902, 2022). "Given that HIV-2/SIV Vpx hijacks the CRL4 (DCAF1) E3 ubiquitin ligase complex to degrade SAMHD1, thereby promoting viral infection, we investigated whether USP37 reverses SIVmac239 Vpx-mediated SAMHD1 degradation." (PMID 39655951, 2025). "We now found that perturbation of DCAF1 led to decreased numbers of naive, effector and memory T cells (major cell types targeted by HIV) under steady state and the abrogation of T-cell response towards virus infection." (PMID 26728942, 2016).
osteosarcoma (4 papers, 2016 to 2023). A usually aggressive malignant bone-forming mesenchymal neoplasm, predominantly affecting adolescents and young adults. "One limitation of our studies is that we did not screen for DCAFs that associate with CUL4B in osteosarcoma cells; instead, we only examined the expression of DCAF1, 4, 8, 11 and 15, and not the expression of other DCAFs." (PMID 28446751, 2017). "By examining the protein levels of several DCAFs in osteosarcoma cells, we found that DCAF11 was specifically upregulated, whereas other DCAFs, such as DCAF1, 4, 8, and 15, were not, and we then determined the interactions between DCAF11 and DDB1." (PMID 28446751, 2017). "The CUL4B-Flag immunocomplex from hFOB1.19, U2OS or Saos-2 cells pulled down DCAF4 and DCAF11, but not DCAF1, 8 and 15, indicating that these two DCAFs form complexes with CUL4 and DDB1 in osteosarcoma cells." (PMID 28446751, 2017).
meningioma (3 papers, 2020 to 2024). A generally slow growing tumor attached to the dura mater. "We show that increased DCAF1 protein expression further increases CRL4-DCAF1 activity in Merlin-deficient meningioma and schwannoma." (PMID 32629964, 2020). "In addition, the researchers also confirmed that the use of MLN3651 or knocking down DCAF1 can lead to the loss of activity of KSR1 protein in meningioma cells, which in turn lead to the inactivation of the Raf/MEK/ERK pathway, inhibiting the proliferation of meningioma cells." (PMID 39564524, 2024). "We explored if the reduced activation of the Raf/MEK/ERK pathway was mirrored in meningioma following DCAF1 knockdown." (PMID 32629964, 2020). "We used meningioma tissue and primary cells derived from meningioma tumours to investigate the expression of DDB1 and Cullin 4-associated factor 1 (DCAF1) and KSR1, and confirmed these proteins were overexpressed." (PMID 32629964, 2020). "However, a reduction of pERK1/2 in response to DCAF1 knockdown was only observed in some meningioma samples, providing a rationale for combination therapy targeting DCAF1 and Raf/MEK/ERK." (PMID 32629964, 2020). "Here, we aim to further characterise the expression of DCAF1 and KSR1 in Merlin-deficient grade I meningioma (herein referred to as meningioma), and assess the therapeutic potential of targeting these proteins/pathways using the neddylation inhibitor MLN3651, and the MEK1/2 inhibitor selumetinib." (PMID 32629964, 2020). "Interestingly, DCAF1 knockdown in primary Merlin-deficient schwannoma samples led to a significant decrease in pERK activity, suggesting that Raf/MEK/ERK activity is more dependent on KSR1 activation in schwannoma than in meningioma." (PMID 32629964, 2020). "DCAF1 and KSR1 were significantly overexpressed in meningioma cells compared to normal human meningeal cells (HMC) (p < 0.05 and p < 0.01, respectively)." (PMID 32629964, 2020). "In vitro, we observed variability in the DCAF1 and KSR1 expression in cultured primary meningioma cell samples." (PMID 32629964, 2020). "We show that DCAF1 knockdown did not change the levels of KSR1 protein in meningioma, and therefore DCAF1 is unlikely to target KSR1 for proteasomal degradation." (PMID 32629964, 2020). "There was variation in DCAF1 and KSR1 expression between different meningioma samples." (PMID 32629964, 2020). "We investigated both DCAF1 and KSR1 expression in meningioma." (PMID 32629964, 2020). "There could be a feedback mechanism in meningioma that permits pERK1/2 activation independent of KSR1 in DCAF1-depleted cells." (PMID 32629964, 2020). "We confirmed that DCAF1 knockdown in meningioma did not alter KSR1 protein levels." (PMID 32629964, 2020).
autoimmune disease (2 papers, 2016 to 2021). A disorder resulting from loss of function or tissue destruction of an organ or multiple organs, arising from humoral or cellular immune responses of the individual to their own tissue constituents. "We next examined whether DCAF1 controls T-cell function in an autoimmune disease model, experimental autoimmune encephalomyelitis (EAE), by immunizing mice with myelin oligodendrocyte (MOG) peptide emulsified in complete Freund's adjuvant (CFA)." (PMID 26728942, 2016).